INS (insulin)
Diseases named in the same sentence as INS in open-access papers (continued):
Sharing a sentence is not in itself a finding about the gene and the disease.
diabetes (continued). "Increasing evidence indicates that abnormal sphingolipid metabolism is deeply involved in the metabolic reprogramming of diabetes (especially T2DM) by interfering with insulin signaling, inducing chronic inflammation, destroying mitochondrial function, and promoting β-cell apoptosis." (PMID 40979718, 2025). "Along with weight gain and obesity, other mediating factors for diabetes development may include modulation of insulin secretion, insulin resistance, hyperlipidaemia resulting in abnormal glucose metabolism, or impaired pancreatic beta-cell response." (PMID 40471419, 2025). "Additionally, physician assistant/physician groups prescribed basal insulin, the second most common diabetes medication after metformin, reinforcing the notion that nurse practitioners and physician assistants are effective in managing chronic diseases." (PMID 39802219, 2025). "One might stem from the need to adopt intensive dietary interventions to control GDM during pregnancy, frequently accompanied by insulin or other types of diabetes medication." (PMID 39980013, 2025). "Since its discovery, insulin has been widely used to treat diabetes." (PMID 40641746, 2025). "Regarding diabetes treatment, 84.6% of all individuals (76.9% of females and 88.5% of males) used oral hypoglycemic agents and 48.7% (46.2% of females and 50.0% of males) used insulin." (PMID 40507026, 2025). "Type 1 diabetes mellitus (T1DM) results from insulin deficiency, while type 2 diabetes mellitus (T2DM) is characterized by insulin resistance often accompanied by an insufficient compensatory insulin secretion." (PMID 40560016, 2025). "However, two patients developed persistent chronic pancreatic pseudocysts, and one patient developed diabetes mellitus, necessitating long-term insulin therapy following the occurrence of AAP." (PMID 40641923, 2025). "We found that these medications could reduce daily insulin needs by 5–8 units per person while also reducing complications from diabetes." (PMID 40245017, 2025). "The contrasting findings might be attributed to underlying differences in the pathophysiology of glucose metabolism and insulin signaling between healthy individuals and those with diabetes." (PMID 40433409, 2025). "However, we did not observe any associations between hourly physical activity levels and fasting glucose, and the associations with fasting insulin and HOMA-IR were also weaker than those observed for diabetes and 2 h OGTT results." (PMID 39982484, 2025). "Although primarily used in the treatment of diabetes mellitus, these medications and exogenous insulin have been implicated in non-diabetic use cases." (PMID 40648766, 2025). "The majority of patients (n = 112, 80%) required insulin treatment for diabetes." (PMID 40076719, 2025). "Secondly, the intervention compliance was self-reported, but we believe the low initial HbA1c (suggesting excellent compliance to diabetes regimen) and the decrease in the insulin dose throughout the LCD period (data shown elsewhere) allow us to presume high compliance of the study participants." (PMID 40846804, 2025). "All participants managed their diabetes using continuous subcutaneous insulin infusion." (PMID 40217942, 2025). "We found that women using "insulin only" had a higher risk of all-cause mortality than women without diabetes." (PMID 41350985, 2025). "Research on the pathogenesis of diabetes has shown that diabetes is a syndrome characterized by abnormalities in glucose and lipid metabolism, with the core manifestations being insufficient insulin secretion and/or insulin resistance." (PMID 40941440, 2025). "Similarly, non-invasive insulin delivery via DPIs offers a promising alternative for diabetes management, mimicking subcutaneous injection pharmacokinetics while enhancing patient comfort." (PMID 40005989, 2025).
diabetes (continued). "Impaired catabolism of branched-chain amino acids—modulated by pathogenic variants in BCKDHA and loss-of-function alleles in PPM1K—compromises tissue-selective disposal of these metabolites, thereby fostering insulin resistance and accelerating the progression of type 2 diabetes mellitus." (PMID 41190158, 2025). "Similarly, in a study by Abdulyemmah and Majeed, it was stated that the local vibration technique was an effective non-invasive method of reducing pain during subcutaneous insulin injections in adults with type 2 diabetes mellitus." (PMID 41216198, 2025). "These compounds improve insulin sensitivity, which is essential for people with diabetes." (PMID 40284028, 2025). "Neither diabetes duration ≥ 10 years (OR 1.04, 95% CI: 0.97–1.11) nor use of oral glucose‐lowering medications (OR 1.03, 95% CI: 0.94–1.12) or insulin (OR 0.99, 95% CI: 0.91–1.07) were associated with vaccination." (PMID 41388482, 2025). "Consequently, the production of mature insulin is significantly decreased, potentially impairing glucose metabolism and, in severe cases, contributing to diabetes development." (PMID 40109403, 2025). "Deficits in executive function are also common and may affect the ability to perform tasks such as glucose testing and decisions about how much insulin to take with downstream effects on diabetes management." (PMID 40403025, 2025). "Notably, they hold promise in diabetes prevention and treatment by regulating insulin secretion and improving insulin resistance." (PMID 40278263, 2025). "One mechanism that may explain why GlyFn increases in women with preeclampsia and/or diabetes mellitus is insulin resistance and inflammation." (PMID 40676555, 2025). "The most favorable outcomes, specifically regarding increased TIR, reduced TAR and TBR, and lower GRI were observed in study participants previously treated with insulin pumps, worse baseline glycemic control (HbA1c ≥ 7.0%), lower BMI, longer duration of diabetes (>15 years)." (PMID 41473236, 2025). "Overall, our findings indicate that SchA may mitigate the effects of diabetes-related cortical inflammation, insulin resistance, and iron overload, safeguarding synaptic and neuronal plasticity and eventually resolving cognitive impairment." (PMID 40589410, 2025). "This family also produces unique secondary metabolites, such as grayanane diterpenes found almost exclusively in Ericaceae, which display bioactivities relevant to diabetes (notably the inhibition of protein tyrosine phosphatase 1B, a negative regulator of insulin signaling)." (PMID 40430501, 2025). "Insulin treatment is considered one of the most effective diabetes treatment interventions." (PMID 40336418, 2025). "Most diabetes subgroups had lower all-cause mortality risk than those without diabetes, except for women using “insulin only”, underscoring the need for individualized HCS." (PMID 41350985, 2025). "Anthocyanins have enhanced insulin sensitivity, which is critical to glycaemic control in diabetes." (PMID 39136514, 2025). "Continuous glucose monitoring can support stable intraoperative glycaemic control and may facilitate more precise insulin management during caesarean section and postoperative period in patients with pregestational diabetes." (PMID 41010874, 2025). "As an example, in Asian patients, diabetes develops at a younger age and is characterized by early cell dysfunction in the setting of insulin resistance, which may require early insulin treatment." (PMID 40364186, 2025). "Furthermore, there is significant controversy over the impact of red meat on the disease burden of diabetes, and there are different conclusions regarding its effects on blood glucose and insulin biomarkers." (PMID 40219013, 2025). "Her diabetes remained well controlled on insulin pump therapy, with HbA1c of 7.0%." (PMID 41341138, 2025).
diabetes (continued). "Glycemic outcomes were assessed by time-to-event analysis of a hyperglycemic (two PG measurements ≥ 11.1 mmol/L), severe hyperglycemic (PG > 20 mmol/L), hypoglycemic (< 3.8 mmol/L) event or use of insulin, adjusted for age, diabetes status, hospital site, and mechanical ventilation." (PMID 40665171, 2025). "Additional predictors included insulin use (AUC = 0.66, p < 0.001), ΔTriglyceride (AUC = 0.65, p < 0.001), BMI (AUC = 0.63, p = 0.002), diabetes duration >10 years (AUC = 0.62, p = 0.004), and ΔHDL (AUC = 0.61, p = 0.016), each providing more modest predictive value." (PMID 41008733, 2025). "Insulin was initiated shortly after the diagnosis of diabetes followed by metformin." (PMID 40842493, 2025). "Another hypothesis linking lower serum triglycerides and the risk of cancer development is that in patients with an immune compromise status such as diabetes mellitus, reduced insulin secretion results in the downregulation of triglyceride synthesis." (PMID 39883280, 2025). "Women prescribed insulin only showed a higher all-cause mortality risk compared to women without diabetes." (PMID 41350985, 2025). "Our findings also showed that patients using CSII had better results in terms of quality of life (QoL), although it is worth noting that the literature suggests that diabetes-related distress improves after starting isCGM in both modalities of insulin administration." (PMID 40863228, 2025). "Furthermore, it is thought that older adults in HCN tend to be prescribed insulin more often than other diabetes medications." (PMID 40777704, 2025). "Furthermore, TMAO promotes diabetes by elevating fasting insulin, increasing insulin resistance (HOMA-IR), and inducing adipose tissue inflammation, contributing to glucose metabolism dysfunction and heightened cardiovascular event risks in diabetic patients." (PMID 40777990, 2025). "Weekly insulin represents an innovative approach to diabetes management." (PMID 39810242, 2025). "Similarly, a separate trial demonstrated that insulin pump therapy effectively and safely improved diabetes management, reducing insulin requirements while sustaining improvements in lipid profile and blood pressure among individuals with type 2 diabetes." (PMID 41146752, 2025). "Additionally, fluctuations in insulin levels and other nutritional factors in diabetes can affect the expression of ion channels in individuals with diabetes." (PMID 40650956, 2025). "The administration of the LP HII01 strain in streptozotocin-induced diabetes in adult male Wistar rats resulted in improved glycemic and lipid parameters and insulin-stimulated glucose uptake, together with modulation of gut microbiota composition and reduction of endotoxemia." (PMID 40284576, 2025). "A total of 58.2% of the respondents also correctly found that the usual cause of diabetes is a lack of effective insulin in the body, while another 58.1% indicated that diabetes cannot be caused by the failure of the kidneys to keep sugar out of the urine." (PMID 41537571, 2025). "Additionally, the antidiabetic activity of the extracts was evaluated in the glucose-induced diabetes model of β-TC cells (pancreatic β cells) by measuring glucose and insulin levels of the β-TC cells." (PMID 41304906, 2025). "Among the studies that reported criteria for the detection of diabetes mellitus, some considered a previous diagnosis or glucose records ≥7.0 mmol/L or use of hypoglycemic agents/insulin and others considered a medical diagnosis or fasting glucose records of ≥126 mg/dL or HbA1c ≥ 6.5%, or treatment." (PMID 41170326, 2025). "Diabetes develops when the body cannot effectively control blood glucose levels, due to issues with insulin production in the beta cells or inadequate responses to insulin in target tissues." (PMID 41373704, 2025). "Non-insulin medications also contribute significantly to financial burden with diabetes." (PMID 40358737, 2025).
diabetes (continued). "Finally, liver transplantation, as seen in our patient, can reverse diabetes in the majority of patients by restoring normal insulin sensitivity." (PMID 40491591, 2025). "Some of these individuals may have also received insulin and/or oral medication to manage their diabetes when necessary." (PMID 40045330, 2025). "The slight decrease in insulin therapy in our study contrasts with increased use in other studies and might be due to difficulties in controlling diabetes, as indicated by the relatively low control rates consistently found in all surveys." (PMID 39940012, 2025). "Additionally, diabetes-related factors, such as glycated hemoglobin (HbA1c) levels, fasting insulin levels, and body mass index (BMI), were evaluated for their potential causal effects on the risk of PE." (PMID 40361863, 2025). "Its potential to enhance insulin sensitivity, combat oxidative stress, and improve overall nutritional status positions it as a holistic and accessible intervention for comprehensive diabetes management." (PMID 40083990, 2025). "We assessed the impact of initiating intermittently scanned continuous glucose monitoring (isCGM) compared with capillary blood glucose monitoring (BGM) on HbA1c levels and hospitalisations for diabetes-related complications in adults with insulin-treated type 2 diabetes in Sweden." (PMID 39460755, 2025). "Diabetes can be defined as a condition with multiple causes that occurs when there is chronic hyperglycemia due to low or no production of the hormone insulin, as well as its ineffective use." (PMID 41373952, 2025). "Besides optimization of insulin delivery, pregnant women with existing diabetes need close monitoring of complications such as hypertensive disorders, diabetic ketoacidosis (DKA), and fetal growth anomalies that can threaten the life of both mother and baby." (PMID 40125239, 2025). "In addition, elucidating how RPE-derived insulin is regulated under conditions of metabolic stress, such as diabetes or retinal degeneration, will play a pivotal role in understanding the role of local insulin release in disease pathophysiology." (PMID 41301488, 2025). "It is well established that diabetes and AD share several pathological features, including impaired insulin signaling, dyslipidemia, decreased levels of choline acetyltransferase, increased production of AGEs and inflammatory mediators, as well as the accumulation of Aβ peptides and tau proteins." (PMID 41009358, 2025). "A study of 599 women with GDM revealed that while insulin treatment reduced birth weight, it did not lower the risk of developing diabetes at either 3 or 12 months postpartum." (PMID 40076938, 2025). "Mutations in a single gene that impact insulin action or β-cell function cause monogenic diabetes, not limited to maturity-onset diabetes of the young (MODY), neonatal DM (NDM), and mitochondrial DM." (PMID 39982365, 2025). "Diabetes mellitus poses a significant global health challenge, and strategies that reduce reliance on insulin or other medications could substantially improve patient management." (PMID 41007307, 2025). "The management of diabetes mellitus involves various strategies such as modification of diet, lifestyle change, intake of oral antihyperglycemic drugs, and/or exogenous administration of insulin depending on the disease subtype." (PMID 40822470, 2025). "This insinuates that targeting the gut microbiota with probiotics or postbiotic metabolites may offer promising, natural strategies for improving insulin function and managing diabetes and related metabolic disorders." (PMID 40806100, 2025). "This study provides compelling evidence that XBL exerts significant therapeutic effects in T2DM rats, improving glycemic control, enhancing insulin sensitivity, regulating lipid metabolism, and protecting pancreatic and renal tissues from diabetes-induced injury." (PMID 41299966, 2025).
diabetes (continued). "Beyond oncology, these inhibitors may hold promise for treating metabolic disorders such as diabetes by influencing amino acid availability and modifying insulin signaling pathways." (PMID 40469683, 2025). "Hence, combining GLP-1RAs with insulin has emerged as a promising approach for achieving diabetes remission." (PMID 41427055, 2025). "This dramatic swing highlighted his insulin sensitivity and raised concern for brittle diabetes." (PMID 41146800, 2025). "This layered control is particularly important in metabolic pathways and stress responses, where PTMs fine-tune insulin signaling, organelle quality control, and cell fate decisions that influence the development and progression of insulin resistance and diabetes." (PMID 41373704, 2025). "Insulin and C-peptide assessment are important in characterization and management of diabetes." (PMID 40587435, 2025). "The term iCGM refers to integrated CGM (iCGM), which are systems that meet specific and rigorous requirements of the FDA with published performance data verifying accuracy that are used to directly inform decision-making in the treatment of diabetes (i.e., insulin dosing)." (PMID 40671052, 2025). "Differentiating MODY from other types of diabetes has major implications; it prevents unnecessary lifelong insulin use, allows cost-effective sulfonylurea therapy, facilitates early detection and management of diabetes in family members, and enables genetic counseling." (PMID 40777711, 2025). "Indeed, this phenomenon of increased insulin clearance has been previously reported in patients with early onset T2D diabetes and normal insulin sensitivity." (PMID 40687579, 2025). "However, in patients with diabetes, particularly those requiring insulin therapy, this inhibitory action is often blunted due to platelet insulin resistance and chronic exposure to hyperglycemia-induced oxidative stress." (PMID 41301135, 2025). "In a clinical setting, this could indeed be crucial for a person living with diabetes to adjust an insulin bolus, to prevent a hypoglycemic episode, to select the appropriate nutritional and exercise plan, and to promote better treatment adherence." (PMID 40703625, 2025). "A pertinent question is whether insulin administration is advantageous for patients with type 2 diabetes mellitus and insulin resistance." (PMID 40564010, 2025). "Furthermore, among patients with diabetes, we examined disease duration (≥5 years vs. <5 years) and insulin use." (PMID 41464593, 2025). "Type 1 diabetes mellitus (T1DM) is an autoimmune condition marked by the T-cell-driven destruction of insulin-producing β-cells in the pancreas, resulting in total insulin deficiency and a lifelong need for insulin replacement." (PMID 40863099, 2025). "In a separate study, Rodríguez and colleagues discovered that even low doses of QE (2.5 mg/kg) could enhance peripheral insulin sensitivity in mice with streptozotocin-induced diabetes." (PMID 40807271, 2025). "This case highlights a patient with brittle diabetes and prior partial pancreatectomy who transitioned to type 3c diabetes mellitus (T3cDM), manifesting as markedly labile glycemia and exaggerated sensitivity to insulin." (PMID 41146800, 2025). "The link between hyperglycemia and TXNIP in diabetes has been extensively documented in pancreatic beta cells and in insulin target tissues, involving mechanisms of glucose-stimulated insulin secretion and sensitivity, glucose uptake, beta cell apoptosis, and inflammation." (PMID 40559375, 2025). "Therefore, it is expected to develop a new treatment strategy for the uric acid insulin axis to prevent or treat diabetes and its complications by regulating the expression of related genes or uric acid level." (PMID 40092731, 2025). "In humans, mutations in the INS gene—including the C96Y variant—have been associated with neonatal diabetes, and the Akita mouse is widely regarded as a relevant model for MODY-like monogenic diabetes." (PMID 41323015, 2025).